OR8G5 (olfactory receptor family 8 subfamily G member 5)
Description:
Odorant receptor.
Synonyms: OR8G5P; OR8G6; OR11-298
Gene: Protein-coding gene on chromosome 11 (124,256,376 to 124,266,224, forward strand). Ensembl gene ENSG00000255298.
Subcellular location: Cell membrane
Pathways (Reactome):
Sensory Perception: Expression and translocation of olfactory receptors
Genetic constraint (gnomAD): Loss-of-function variants: 1 observed, 0.29 expected, observed/expected ratio (o/e) 3.45. That is too few expected variants to judge how well the gene tolerates losing a copy. Missense variants: 347 observed, 378.49 expected, observed/expected ratio (o/e) 0.92, 90% interval 0.84 to 1. Synonymous variants: 147 observed, 151.32 expected, observed/expected ratio (o/e) 0.97, 90% interval 0.85 to 1.11.
Homologues: Orthologues: chimpanzee OR8G5 (97% identical), macaque OR8G5 (93% identical), dog OR8G5 (81% identical), rat Or8g20 (78% identical), mouse Or8g20 (77% identical), mouse Or8g21 (77% identical), rat Or8g21 (76% identical), mouse Or8g23 (76% identical), rat Or8g23 (76% identical), rat Or8g20b (73% identical), mouse Or8g17 (72% identical), rat Or8g20e (72% identical), and 18 more. Paralogues in human: OR8G1 (85% identical), OR8G3 (75% identical), OR8G2P (72% identical), OR8A1 (65% identical), OR8B3 (64% identical), OR8B8 (64% identical), OR8B2 (64% identical), OR8D1 (62% identical), OR8D2 (60% identical), OR8D4 (59% identical), OR8B12 (59% identical), OR8B4 (58% identical), and 84 more.
Diseases named in the same sentence as OR8G5 in open-access papers:
OR8G5 is named in the same sentence as 2 diseases in open-access papers, as found by Europe PMC text mining. Sharing a sentence is not in itself a finding about the gene and the disease. The quoted sentences say what the papers report.
tumor (1 paper, 2024). "Notably, genes, such as DDX11 (12p11.21), IGLV2-18 (22q11.22), OR8G5 (11q24.2), PARP4 (13q12.12), USP10 (16q24.1), and ZNF208 (19p12), exhibited multiple mutations and demonstrated tumor-driving effects." (PMID 39711964, 2024).
OR8G5 also shares sentences with these, for which no sentence is quoted: breast carcinoma (1 paper).